AR (androgen receptor)
Diseases named in the same sentence as AR in open-access papers (continued):
Sharing a sentence is not in itself a finding about the gene and the disease.
prostate carcinoma (continued). "Despite the plethora of knowledge regarding the phosphorylation of AR and its coactivators (e.g., by MAPKs, CDKs) in prostate cancer, only limited evidence exists for non-genomic crosstalk of AR with kinases." (PMID 37686465, 2023). "It has been shown that the androgen signaling pathway plays an important role in prostate cancer progression even at the CRPC stage, and inhibition of the androgen receptor pathway signaling can improve the antitumor efficacy of chemotherapeutic drugs against CRPC." (PMID 37514059, 2023). "Prostate cancer cell lines, including those lacking AR expression (PC3 and DU145) and those with NE phenotype (MSKCC EF1, NCI-H660), demonstrated IC50s that ranged from 0.82 to 42.2 nmol/L (mean 9.3 nmol/L)." (PMID 37823778, 2023). "Prostate cancer therapy suffers from a lack of effective targets because, typically, success with blockade of the androgen receptor gives way to drug resistance and lethal disease relapse." (PMID 38201488, 2023). "The multifaceted mechanisms enable MSAs to not only suppress AR-negative prostate cancer cell proliferation via the cell mitosis pathway, but also to interfere with the AR signaling pathway in AR-positive cells." (PMID 37444418, 2023). "In prostate cancer cells, ARV-771 could restrain androgen receptor signaling and androgen receptor levels to inhibit tumor growth." (PMID 36770884, 2023). "Brassicasterol has been reported for its anticancer activity in prostate cancer, which was attributed to AKT and AR dual-targeting signaling, and in bladder cancer through its androgen receptor (AR) antagonist action and AR (androgen receptor) expression-reducing effect in bladder epithelial cells." (PMID 37960136, 2023). "In some CRPC patients, especially who received ADT treatment, the AR signaling pathway gradually loses its dominant position and is supplanted by some pathways such as ERK or AKT signaling pathways to drive the progression of prostate cancer." (PMID 37095108, 2023). "The critical role of AR as a regulator of DDR genes has been previously reported, leading to the combination of DDR inhibitors and AR deprivation therapy as a new treatment strategy for aggressive prostate cancer." (PMID 38155939, 2023). "Moreover, in prostate cancer, GATA2 has been well-characterized as a critical pioneer TF for AR, whereas GATA2 can mediate PTX resistance by AR-independent regulation of IGF2." (PMID 38126976, 2023). "Inavolisib is under clinical development for breast cancer, with no published applications related to AR signaling or for the indication of prostate cancer." (PMID 36768610, 2023). "This implies that JNJ-64619178 impairs the repair of radiation-induced DSBs better than ASIs in prostate cancer cells independent of AR." (PMID 36959798, 2023). "TMPRSS2 is also strongly related with other genes involved in prostate cancer, like ERG, ETV5 and AR, whose characterization could help to clearly classifying COVID-19." (PMID 37287057, 2023). "Finally, CDK5 also shows significant crosstalk with the PI3K-Akt cascade in prostate cancer cell proliferation since CDK5 seems to physically interact with Akt to control Akt membrane sequestration and androgen receptor-mediated activation." (PMID 36791155, 2023). "Better molecular markers are required to specifically identify and eradicate prostate cancers that exhibit resistance to hormone therapy due to a lack of androgen-receptor (AR)." (PMID 38213538, 2023). "Since prostate cancer cell growth is AR dependent we consider the lack of AR expression changes responsible for the absence of cell viability variations following treatment with dutasteride." (PMID 37569712, 2023). "Recently, a novel prostate cancer classification based on gene expression profiles from the PI3K and AR pathways has been proposed, and a worse progression-free survival was evidenced for the subgroup with a mixed PI3K and AR signature." (PMID 36768610, 2023).
prostate carcinoma (continued). "Immune checkpoint inhibitors that target cytotoxic T-lymphocyte-associated protein 4 (CTLA-4), programmed death 1 (PD-1), and its ligand (PD-L1) display minimal or no activity as single agents or in combination with AR inhibitors in advanced prostate cancers." (PMID 36776288, 2023). "AR or ER antagonists boost the antitumor activity of ferroptosis inducers in AR+ prostate cancers and ER+ breast cancers with or without resistance to single-agent hormone therapies." (PMID 38072908, 2023). "Forced expression of LBCS inhibited prostate cancer viability, whereas LBCS depletion sustained prostate cancer viability by blocking AR signaling in the absence of androgen." (PMID 36674820, 2023). "In prostate cancer, EZH2 functions both as an epigenetic writer and AR coregulator." (PMID 38001678, 2023). "In addition, by promoting androgen receptor (AR) nuclear translocation, CYP3A5 governs the proliferation of prostate cancer cells." (PMID 36983670, 2023). "Androgen’s ability to increase DRP-1 amount has been observed in prostate cancer, where, however, in contrast to breast cancer, AR has a negative prognostic value." (PMID 37686282, 2023). "The PC-3 cell line is one of the most frequently used models for androgen-independent prostate cancers due to its very low or lack of AR expression." (PMID 36835012, 2023). "Together, these results demonstrate that the loss of LCMT1/decreased PP2A-C α-carboxymethylation is a major determinant of AR-addicted PCa and supports the therapeutic use of AR degraders and selective small molecule modulators of PP2A for refractory prostate cancer treatment." (PMID 37644036, 2023). "Prostate cancer cells can also repair DNA damage after radiation therapy independent of AR pathways." (PMID 36959798, 2023). "In conclusion, AR knockdown results in the inactivation of the ERK/ELK‐1 signalling pathway that, in turn, leads to the downregulation of FEN1 and improves the DTX sensitivity of prostate cancer cells." (PMID 37326412, 2023). "NED was targeted with JNJ-64619178 in androgen receptor (AR) positive and negative prostate cancer cells undergoing FIR treatment." (PMID 36959798, 2023). "Particularly, in the prostate cancer study, an AR-negative cell line was tested, although the role of AR signaling in its progression and treatment has been extremely well established." (PMID 37762034, 2023). "We confirmed the regulatory effect of AR on FEN1, pho‐ERK1/2 and pho‐ELK1 in prostate cancer cells." (PMID 37326412, 2023). "On the other hand, USP12 promoted prostate cancer (PC) cells proliferation by forming a complex with Uaf-1 and WDR20 and deubiquitinating AR, thereby increasing AR stability and transcriptional activity, whereas USP12 silencing led to a significant decrease in PC cell proliferation." (PMID 37752518, 2023). "None of the remaining commonly used prostate cancer cell lines that express the wild-type AR isoform (RWPE-2, DUCaP, LAPC, PC346 and VCAP) originate from the primary site." (PMID 37264224, 2023). "The majority of those cancer cells are AR+CXCR2− luminal cancer cells, but there are also AR−CXCR2+ neuroendocrine cancer cells, which account for about 0.5% of all tumor cells in low-grade prostate cancer to 20% in metastasis prostate cancer." (PMID 37108425, 2023). "Hence, the effects of the combined targeting of AR and PTEN/AKT pathways in the setting of localized prostate cancer need to be investigated." (PMID 36768370, 2023). "This inhibitor also reduced the proliferation of androgen-dependent (AR+) prostate cancer LAPC-4 cells but not the proliferation of (AR-) prostate cancer PC-3 cells, suggesting an effect mediated via the reduction of the production of androgens." (PMID 37110733, 2023).
prostate carcinoma (continued). "Despite liganded AR mainly repressing the transcription of tumor suppressor genes, androgen treatment also induces transcriptional activation in AR-expressing KYSE410 cells, which is similar to the dual functions of AR-mediated gene regulation in prostate cancer." (PMID 38136265, 2023). "It has been reported that DDR genes in prostate cancer cells get upregulated by PRMT5 upon radiation treatment independent of AR." (PMID 36959798, 2023). "We also reported that prostate cancer cells require PRMT5 to repair IR-induced DNA damage independent of AR." (PMID 36959798, 2023). "Prostate cancer development and progression depend on androgen receptor (AR) signaling, and the HSF1-activated multichaperone complex (HSP90, HSP70, and HSP40) plays a crucial role in maintaining AR stability." (PMID 37351671, 2023). "SHOT-RNAs are abundantly expressed in androgen receptor (AR)-positive prostate cancer cell lines LNCaP-FGC cells, but not AR− DU145 and PC-3 cells." (PMID 36782290, 2023). "However, in prostate cancer cells, ANXA7 is often downregulated, leading to increased AR signaling and cancer cell proliferation." (PMID 37240163, 2023). "Guan H reported that the BRD4/AR signaling pathway was significantly activated when progressing from ADPC to CRPC, and miR-200a could suppress prostate cancer progression by inhibiting this signaling pathway." (PMID 35184651, 2022). "Early-stage prostate cancer can be treated by androgen deprivation therapy to lower the levels of androgens or by antiandrogens, which compete with androgens for binding to the LBD of AR." (PMID 35966880, 2022). "Indeed, counter-regulation of PI3K and AR signaling has been found in prostate cancer, where PTEN deletion reduces AR activity and inhibition of AR results in activation of PI3K/Akt signaling." (PMID 36551650, 2022). "Currently, one of the significant challenges in the field of prostate cancer research is still the lack of appropriate animal models that can recapitulate the oncogenic role of AR during prostate cancer initiation, progression, and hormone refractoriness." (PMID 35902588, 2022). "A dynamic regulatory relationship between the androgen/AR signalling and ZFHX3, both of which modulate prostate cancer development and progression, could have therapeutic implications." (PMID 34953044, 2022). "However, prior reports suggesting roles for CAMKK2 in an AR- cell line in culture and here in vivo indicate roles for CAMKK2 even in AR-indifferent prostate cancers." (PMID 35741020, 2022). "In this article, we will review the scientific rationale, preclinical and early clinical data, and future possibilities of one such approach that combines AR and poly (ADP-ribose) polymerase (PARP) inhibition to induce synthetic lethality in prostate cancer cells." (PMID 35159068, 2022). "Together, this suggests an interaction between AR activity and KDM5D in prostate cancer biology." (PMID 36087093, 2022). "Notably, AR, MYC and E2F1/2 are all established Hsp90 client proteins, and targeting Hsp90 inhibits expression of AR in prostate cancer, and MYC and E2F1 in other cancers." (PMID 35406480, 2022). "In the first step, we collected prostate cancer-related genes, including growth factor pathway genes such as PTEN, P27, and NKX3.1, which increase cancer cell proliferation and include oncogenes such as AR." (PMID 36251702, 2022). "Previous studies indicate that millimolar concentrations of metformin reduce proliferation of androgen receptor (AR) negative, castration-resistant human prostate cancer cell lines." (PMID 36175875, 2022). "A shorter isoform of AR primarily expressed in castration-resistant prostate cancer (CRPC), ARv7, indicates poorer prognosis in prostate cancer (PCa), as it lacks the LBD and remains overly active even in absence of the hormone, the mechanism of which is still not fully understood." (PMID 36388907, 2022).
prostate carcinoma (continued). "Moreover, androgen receptor and TRIM24 co-activated genes are significantly upregulated in castration-resistant state prostate cancer." (PMID 35105347, 2022). "Although the majority of human prostate cancer cell lines are said to be AR-negative, multiple studies have found that the AR mRNA is expressed at measurable quantities in the PC-3 and DU-145 prostate cancer cell lines." (PMID 36517571, 2022). "As a control, we also tested metformin in PC-3 cells, a castration-resistant human prostate cancer cell line that expresses little to no AR." (PMID 36175875, 2022). "Advanced prostate cancer is refractory to ICB, however the clinical trial (NCT02312557) evaluating dual therapy with AR inhibition and anti-PD-1 ICB achieved a response rate of 18%, underscoring the importance of AR signaling axis in mediating resistance to ICB." (PMID 36337733, 2022). "In this review we summarise the development and expanding role of PARPi in prostate cancer including biomarkers of response, the relationship between the androgen receptor and PARP, evidence for combination therapeutics and the future directions of PARPi in precision medicine for prostate cancer." (PMID 36497408, 2022). "Due to its favorable physical-chemical properties and high selectivity, [44Sc]Sc-NODAGA-AMBA seems to be a promising molecular probe for PET imaging of PSMA and AR-negative prostate cancers and metastases." (PMID 36077458, 2022). "Thus, the alterations to the AR cistrome observed by Pomerantz and colleagues in mCRPC, such as those associated with prostate developmental programs, may be more relevant for prostate cancer metastasis, rather than the development of castration-resistance per se." (PMID 36212399, 2022). "Zhu and Kyprianou showed that androgens and AR signalling can result in an EMT induction, although this only occurred in the context of low AR levels and observations were limited to LNCaP and PC-3 prostate cancer cell lines." (PMID 35493092, 2022). "Indeed, in prostate cancer cells, the boundaries established by CTCF showed more effective AR transcriptional regulation than in normal cells." (PMID 35966880, 2022). "This study indicates that prostate cancer engages in classical endocrine negative feedback loops to titrate AR to match the abundance of ligand." (PMID 36194476, 2022). "Indeed, targeting the interaction between AR and SWI/SNF disrupts AR-dependent prostate cancer cellular proliferation." (PMID 36212399, 2022). "Even then, ADT should not be suspended, as prostate cancer cells are still addicted to AR signalling and there is a survival benefit with continued testicular androgen suppression." (PMID 36819799, 2022). "Several studies have demonstrated that somatic mutations in the PI3K-Akt pathway could coordinate PTEN, mTOR, AR, MAPK, Wnt and TGF-β signaling pathways to play an important role in the tumorigenesis, progression, and treatment in prostate cancer." (PMID 36095024, 2022). "Two human prostate cancer cell lines, PC-3 (androgen receptor negative) and 22Rv1 (androgen receptor positive), were also used in the cytotoxicity test." (PMID 36662200, 2022). "The data revealed that Remodelin significantly reduced AR-negative prostate cancer tumor growth, and in the high-dose Remodelin group, xenograft tumor weight at the endpoint was also much smaller than that in the low-dose group." (PMID 35743017, 2022). "In addition to the analysis of prostate cancer patients receiving ADT, studies have also looked at the therapeutic potential of AR signalling inhibitors as a treatment option for COVID in other cohorts of men." (PMID 36560732, 2022). "The differential role of AR-FL and AR-V7 in gene regulation is known; however, it is not yet understood if either AR-FL or AR-V7 transcriptionally regulates TNC expression in prostate cancer." (PMID 35948987, 2022).
prostate carcinoma (continued). "For instance, androgen receptor (AR) negative prostate cancer and neuroendocrine PCa do not express PSA." (PMID 35158943, 2022). "In prostate cancer, NIBAN1 expression is regulated by androgen receptor (AR)." (PMID 35517496, 2022). "Transcriptomic analysis of enzalutamide-resistant prostate cancer cells by us and others also revealed a negative correlation between the expression of TRIB2 and AR signaling-associated genes." (PMID 34973338, 2022). "Indeed, in LNCaP (prostate cancer) cells, another FKBP51 ligand CsA was a highly effective inhibitor of both AR-dependent and -independent proliferation, while FK506 inhibited only AR-dependent growth." (PMID 36139138, 2022). "We anticipate that prostate cancer of diverse histology with low AR activity will not be growth-inhibited by SPA/BAT." (PMID 36194476, 2022). "How prostate cancer cells summon HATs to acetylate AR in response to AR antagonists is not clear and will be the topic of future investigation." (PMID 35704598, 2022). "Overall, these results validate the oncogenic role of miR-22 in prostate cancer, at least in the context of AR-negative prostate cancer." (PMID 36551740, 2022). "It is common for prostate cancer with a NE phenotype to not express prostate cancer–specific biomarkers, AR, NKX3.1, and PSA." (PMID 36643868, 2022). "Our study reveals a novel regulatory mechanism of prostate cancer AR inhibitor resistance, raises the possibility of AR/SRC dual-targeting of castration-resistance of prostate cancer, and lays foundation for the future development of selective inhibitors of GDF15 glycosylation." (PMID 35853851, 2022). "Interestingly, these complexes also inhibit androgen receptor (AR) and prostate-specific antigen (PSA) signaling, which are critical for prostate cancer survival and progression." (PMID 35630591, 2022). "AR alternative splicing (AS) events resulting in the absence of the LBD from AR isoforms is another major resistance mechanism relevant to prostate cancer." (PMID 35864113, 2022). "Bicalutamide, a first-generation non-steroidal androgen receptor (AR) antagonist, has become a key part of prostate cancer (PCa) treatment by acting directly on the AR61." (PMID 36335189, 2022). "They suggest that irrespective of androgen receptor phenotype, prostate tumor cells-derived exosomes considerably boost various mechanisms promoting prostate cancer progression." (PMID 36463254, 2022). "Enzalutamide, a second-generation inhibitor of the AR-signaling pathway, has been approved by the U.S. Food and Drug Administration (FDA) to treat patients with castration-resistant or chemotherapy-resistant prostate cancer." (PMID 36548336, 2022). "Since 2006, it is also discussed that, next to the inhibition of the AR by ADT and antiandrogens, treatment with high testosterone levels also inhibits prostate cancer proliferation and may provide a new therapeutic option." (PMID 35723327, 2022). "It is now well established that most CRPC tumours are not hormone-independent, and that androgen receptor (AR) signalling remains a key driver of resistance and progression in prostate cancer in the phase of castration resistance." (PMID 36547161, 2022). "MAGEB2 could bind to the NH2-terminal NTD domain of AR through the F-box in the MAGE homology domain, and promotes prostate cancer cell growth by upregulating its downstream targets PSA and NX3.1 to activate AR signaling." (PMID 36085146, 2022). "Consistent with this concept, pharmacologically targeting cholesteryl ester synthesis by blocking acyl-Coenzyme A: cholesterol acyltransferase 1 (ACAT1) activity impaired androgen-independent, androgen receptor (AR)-negative PC3 prostate cancer cell growth." (PMID 35033184, 2022). "We first show that MDA-468 cells are AR negative and that BT-549 cells express similar levels of AR to those in the LNCaP prostate cancer cells." (PMID 36230969, 2022).